IL1A (interleukin 1 alpha)
Diseases named in the same sentence as IL1A in open-access papers (continued):
Sharing a sentence is not in itself a finding about the gene and the disease.
pancreatic cancer (continued). "In this study, we investigated the mechanism of activation of FAK and its downstream extracellular signal-regulated kinase (ERK)-1/2 signaling following stimulation by interleukin (IL)-1α and adhesion to ECM with subsequent enhancement of pancreatic cancer cell adhesion and invasion." (PMID 16209712, 2005). "IL-1α-induced activation of these signaling pathways can be inhibited by knockdown of FAK expression with siRNA, consistent with the inhibition of adhesive and invasive capabilities of pancreatic cancer cells." (PMID 16209712, 2005). "SMAD7-silenced PSCs were incubated in the presence or absence of IL-1α, and the effect of PSC-conditioned medium was assessed in a wound closure model using BxPC-3 pancreatic carcinoma cells." (PMID 27473228, 2016). "Knockdown of FAK expression with siRNA inhibited IL-1α-induced Ras/ERK activation with subsequent inhibition IL-1α-induced adhesion and invasion of pancreatic cancer cells on Coll IV while not statistical affecting cellular apoptosis." (PMID 16209712, 2005). "Both of knockdown of FAK expression with siRNA and blocking of β1 integrin inhibited IL-1α-induced Ras/ERK activation with subsequent inhibition IL-1α-induced adhesion and invasion of pancreatic cancer cells on Coll IV while not statistical affecting cellular apoptosis." (PMID 16209712, 2005).
colon cancer (32 papers, 2010 to 2025). "Recent studies have demonstrated that the CaMKIIβ pathway promotes astrocyte proliferation in spinal cord injury by regulating the inflammatory factor IL-1α.CaMKIIγ has been closely linked to colon cancer, whereas CaMKIIδ plays a significant role in osteoarthritis." (PMID 40503232, 2025). "In this study, colon cancer cell-derived IL-1α was also confirmed as the secreted factor that induced the activation of colon CAF." (PMID 41392310, 2025). "The expression level of IL-1A was found to be significantly increased in a variety of cancers, including non-small cell lung cancer, colon cancer, and squamous cell carcinoma." (PMID 38111060, 2023). "The effects of IL-1α and its receptor antagonist IL-1Ra on the migration of colon cancer cells and promoting angiogenesis and the chemotaxis of CXCL12 all play an important role in tumorigenesis and metastasis." (PMID 34930323, 2021). "The up-regulation of IL1A gene has been suggested to play an important role in preventing colon tumor in patients with IBD." (PMID 31114763, 2019). "Inflammatory cytokines such as IL-1α, IL-6 and TNFα are elevated in colon cancer and play important role in the mechanism of tumorigenesis." (PMID 26951793, 2016). "Human colon cancer-derived IL-1α induces angiogenesis by its action upon the microenvironment, and thereby contributes to metastasis." (PMID 23847622, 2013). "In summary, we found that shikonin suppresses colon cancer cell proliferation and migration through cellular experiments and identified eight genes (CCNB3, IL-1α, CXCL8, CDKN2A, MYC, IGFBP3, SQSTM1, and GADD45G) associated with cell senescence through systematic bioinformatics analysis." (PMID 39188951, 2024). "Furthermore, a mouse model of adenomatous polyposis coli (APC) colon cancer showed significant levels of IL-1B and IL-1A." (PMID 37894904, 2023). "Similarly, IL-1α was reported as an essential inflammatory cytokine promoting colon cancer metastasis by regulating angiogenesis and inducing pro-tumor immune cell infiltration via IL-1α/PI3K/NF-kB signaling." (PMID 37835389, 2023). "Specifically, these shared pathways with IBD were linked to inflammation (TNF, IL-1A, IL-1B, NFkB, IL-6) and growth (TREM1, TGFB1), while other pathways shared with colon cancer were associated with colorectal metastatic signaling, growth (TREM1, NFkB and HMGB1) and inflammation (IL-8, IL-6)." (PMID 35323693, 2022). "Indeed, Shao and colleagues showed in their study that IL-1α stimulates the migration of colon cancer cells." (PMID 25237386, 2014). "Overexpression of S100A8/S100A9 in mouse colon cancer cells CT26.WT led to differential increases in the secretion levels of various cytokines (CXCL5, CXCL11, GM-CSF, G-CSF, IL1a, IL1b, sTNF RI, and CCL3)." (PMID 38817853, 2024). "A total of 27 anticolon cancer targets of THCQF were selected, among which four genes (CCNB1, CCNA2, IL1A, and MMP3) were shown to effectively predict patient outcomes in a prognostic colon cancer model." (PMID 35479514, 2022). "It has also been proved that IL-1α is a pro-inflammatory and carcinogenic factor regulated by PGE2, which can stimulate the migration of colon cancer cells." (PMID 34930323, 2021). "C-reactive protein (CRP), albumin, IL-1α, IL-1β, IL-6, IL-8, IL-10, TNF-α, midkine, VEGF-A, VEGF-C, leptin, adiponectin, and ghrelin serum levels are studied in 126 colon cancer patients and 36 healthy subjects." (PMID 20920199, 2010). "However, ablation of GSDMD in sporadic colon tumors did not result in altered IL-1α, IL-1β, and IL-18 as well as NLRP3 or ASC speck formation." (PMID 38898209, 2024).
endometriosis (31 papers, 2015 to 2025). The growth of functional endometrial tissue in anatomic sites outside the uterine body. "Genes associated with endometriosis risk are highly expressed in M2 macrophages, particularly ligands IL1A and IL1B." (PMID 40938538, 2025). "Then, even though assessment of IL‐1α levels in cervico‐vaginal fluid has potential for patient stratification, given the complex nature of endometriosis‐associated inflammation, it is likely that other inflammatory markers also need to be accounted for." (PMID 40938538, 2025). "Population‐scale expression quantitative trait locus analysis demonstrates that genetic variation controlling IL1A expression is associated with endometriosis risk variants." (PMID 40938538, 2025). "This revealed evidence of a shared causal variant between the endometriosis risk variants and a IL1A eQTL." (PMID 40938538, 2025). "There is a genome-wide association study of endometriosis that identified independent loci SNPs (single nucleotide polymorphism) at the IL-1A gene locus, which is associated with endometriosis risk." (PMID 38337827, 2024). "In 2015, an association between IL-1A rs6542095 with moderate-to-severe endometriosis has been detected." (PMID 34445738, 2021). "Multiple GWAS studies in Japanese and European population samples have identified the IL1A gene locus as associated with endometriosis, which was the most common pathological condition related to secondary dysmenorrhea." (PMID 29855537, 2018). "Together, these data suggest that M2 macrophage‐derived IL1A/B could be involved in endometriosis risk." (PMID 40938538, 2025). "Endometriosis‐associated M2 macrophages also express IL1A/B antagonist IL1RN, which may also contribute to fine‐tuning of IL1 signaling and risk conferred by variants at this locus." (PMID 40938538, 2025). "Somewhat unexpectedly, in eQTL analyses, lower IL1A expression was associated with increased risk, suggesting that muted inflammatory responses may be protective against developing endometriosis." (PMID 40938538, 2025). "The IL1A signal might reflect endometriosis because this locus was previously reported to be associated with endometriosis." (PMID 37144689, 2023). "The imbalance between IL-1α, pro-IL-1β, sIL-1R2, and sIL-1RAcP in the PF and serum of endometriosis patents may be linked to the ability to transform acute inflammation into a chronic one." (PMID 32145751, 2020). "This suggests that IL-1α could be an effective non-invasive diagnostic marker for endometriosis." (PMID 39767772, 2024). "In addition, eight loci in the IL1A gene are related to the risk of endometriosis in Japanese population, which supports the involvement of immune and inflammatory responses in the development of endometriosis." (PMID 36358904, 2022). "Endometriosis risk variants in the chromosome 2q14.1 locus were mapped to eQTLs to identify evidence that genetically regulated expression differences in IL1A and/or IL1B are conferred by the same variants associated with endometriosis risk." (PMID 40938538, 2025). "The number and strength of associations for IL1A, and the myeloid‐specific associations for IL1B are further evidence to link these genes to endometriosis risk." (PMID 40938538, 2025). "A study reported that cervico-vaginal fluid levels of IL-1α were substantially higher in women with endometriosis compared to controls." (PMID 39767772, 2024). "IL-17 has been shown to promote the production of other proinflammatory cytokines, such as IL-1α and IL-1β, involved in the pathogenesis of endometriosis." (PMID 39061077, 2024). "Another interleukin involved in endometriosis-related angiogenesis is IL-1α, which promotes this process through the augmented expression of various angiogenic factors such as VEGF, IL-8, and bFGF, according to the results published by Torisu and collab." (PMID 32143439, 2020).
endometriosis (continued). "Results from the analysis of both discovery and replication samples did provide support for near genome-wide significant association for rs6542095 near IL1A and significant association of the splice variant rs13394619 at the GREB1 locus with endometriosis." (PMID 28900119, 2017). "This idea is further supported by studies reporting impaired expression of the soluble decoy receptor IL-1-RII in the endometrium and PF of women with endometriosis, which would help attenuate the effects of IL-1α and IL-1β." (PMID 26247027, 2015). "Arici and colleagues reported that mesothelial cells isolated from the PF of women with endometriosis not only produce MCP-1 in response to IL-1α and TNF-α stimulation, but also constitutively produce the cytokine as well." (PMID 26247027, 2015). "Meanwhile, one study indicates that IL-1α may have significant potential as a biomarker for diagnosing endometriosis." (PMID 39767772, 2024). "In addition, the cytokines IL-1α, IL-6, IL-8, IL-18, and TNFα have been found to increase in endometriosis consistently." (PMID 35628423, 2022). "Increased levels of IL-1α are observed in the peritoneal fluid of women with endometriosis." (PMID 35805112, 2022). "Interestingly, mesothelial cells isolated from the PF of endometriosis patients have been reported to produce IL-8 in response to IL-1α and TNF-α stimulation." (PMID 26247027, 2015). "However, IL-1α is also released from the nucleus when the cell is damaged (like IL-33), and we indeed detected IL-1α in the ascites at 8 hours after transplantation, thus IL-1α may also contribute to the development of endometriosis." (PMID 31507610, 2019). "There was also a tendency for eutopic endometrium from endometriosis cases to express higher IL1R1 and lower IL1A and IL1B." (PMID 40938538, 2025). "Genetic differences play a significant role in risk for endometriosis; a recent meta-analysis of over 170,000 endometriosis patients and almost 200,000 controls revealed 14 genetic regions of interest, including WNT4, GREB1, IL1A, and CDKN2B." (PMID 30134794, 2018). "qRT–PCR data confirmed that the mRNA levels of interleukin 1-α (IL1A) and interleukin 1-β (IL1B) were increased significantly in GSK591-treated decidualized hEnSCs, which was also observed in the endometrium of endometriosis patients." (PMID 36195592, 2022). "In contrast, IL1α but also its antagonist interleukin-1 receptor antagonist (IL1RA), are present in increased amounts in peritoneal fluid of women with endometriosis vs. without endometriosis, but IL1RA is not found in endometriotic lesions." (PMID 41154663, 2025). "IL-1α has been identified as a potential marker for endometriosis, and we observed that it was increased in patients with CPP with and without endometriosis." (PMID 38972981, 2024). "However, the eQTL results should be interpreted with caution as IL1A and IL1B are known to have highly context‐specific effects, and their roles in endometriosis development and symptomatology are not yet completely defined." (PMID 40938538, 2025).
depression (28 papers, 2012 to 2025). "In this study, we aimed to more precisely assess the association between inflammation and depression by measuring inflammatory markers (IL-6, IL-1α, and TNF-α)." (PMID 39595067, 2024). "Although existing studies have primarily focused on the effectiveness of established interventions on IL-1β, IL-1α—being the inducible form released in an inflammatory disease state—may be more closely associated with depression than IL-1β." (PMID 41194929, 2025). "In patients with depression and anxiety inflammatory reaction and mild chronic inflammation were observed to be caused by increased concentration of proinflammatory cytokines like TNFα, IL-1α, IL-1β, IL-4, IL-5, IL-6, IL-12, IFNγ, and C-reactive protein." (PMID 26078821, 2015). "Patients with anxiety and depressive disorders have increased levels of pro-inflammatory cytokines (e.g., TNFα, IL-1α, IL-1β, IL-4, IL-5, IL-6, IL-12, and interferon [IFN]-γ) and C-reactive." (PMID 39803412, 2025). "It was reported that significantly decreased IL1A expression was identified in depression cases compared to controls." (PMID 37065490, 2023). "It is well established that patients with depression and anxiety have higher plasma levels of C-reactive protein and proinflammatory cytokines (e.g., TNFa, IL-1a, IL-1b, IL-4, IL-5, IL-6, IL-12, and interferon)." (PMID 33802143, 2021). "In people with MS with comorbid fatigue and/or depression, there are reported increased serum and CSF concentrations of the pro-inflammatory cytokines, such as interleukins (IL-1a, IL-1b, IL-2, IL-6), TNF-α and IFN-γ." (PMID 35242093, 2021). "In people with MS and comorbid fatigue and/or depression there is reported increased serum and cerebrospinal fluid concentration of inflammatory mediators such as tumor necrosis factor, interleukins (IL-1a, IL-1b, IL-6), interferon γ and neopterin." (PMID 35242093, 2021). "We were also interested in IL-1α levels as many papers in depression focused on IL-1β while neglecting IL-1α." (PMID 29103192, 2018). "A similar trend was observed for pro-inflammatory cytokine IL-1α levels with Abuse+Depression being the highest (2.79 log pg/mL), followed by the Abuse (2.13 log pg/mL) and the Control (1.93 log pg/mL) groups." (PMID 29894487, 2018). "In HIV-uninfected women, we found significantly higher levels of pro-inflammatory cytokine IL-1α and chemokine IP-10 in Abuse+Depression group compared to Controls, indicating inflammation/immune activation." (PMID 29894487, 2018). "Further, there was evidence of significant interactions between chronic sexual abuse and current depression for IL-1α, IP-10, Serpin A1, Cystatin B, and FGF." (PMID 29894487, 2018). "Whereas none of the other mediators showed a differential association with depression by HIV status, the association between abuse and TNF-α (p<0.01), IL-1α (p<0.01) and IP-10 (p<0.01) was significantly lower in HIV infected compared to uninfected women." (PMID 29894487, 2018). "Pro-inflammatory cytokines, such as IL-1α, are known to be positively correlated with depression-like behavior and stress, inducing “sickness behavior”, and this is interesting, as grid floor exposure was also correlated with these same cecal cluster groups." (PMID 23056268, 2012). "Moreover, Lacticaseibacillus paracasei NK112 exerted protective effects against Escherichia coli-induced depression through decreasing the expression of IL-1α, IL-6, and TNF-α, and inhibiting the activity of NF-κB in the hippocampus." (PMID 36358502, 2022). "In addition, Lactobacillus gasseri NK109 improved Escherichia coli K1-induced depression through decreasing the expression level of IL-1α in activated macrophages and regulating gut microbiota via vagus nerve-mediated gut–brain signaling." (PMID 36358502, 2022).
depression (continued). "In conclusion, major depression is characterized by increased sIL-1RA, sTNF-R1, and TBARS concentrations, while the acute phase of depression is accompanied by higher sIL-6R levels (compared with the remitted state) and melancholia by higher sIL-6R but lower IL-1α levels." (PMID 29103192, 2018). "Therefore, the concentrations of cytokines, including IL-1α, IL-1β, and IL-6, were detected by ELISA kits in the serum of mice with restraint stress-induced anxiety and depression." (PMID 30400578, 2018). "This oxidative stress and increased depression lead to demyelination and cerebral atrophy, accompanied by elevated concentrations of inflammatory mediators such as tumor necrosis factor (TNFα) and specifically interleukin IL-6, along with IL-1α and IL-1β, in the serum and CSF." (PMID 37693246, 2023). "ROC curve analysis demonstrated that IL-1α, IL-6, and TNF-α showed high accuracy in discriminating patients with severe depression." (PMID 39595067, 2024). "The predictive value of the cytokines IL-1α, IL-6, and TNF-α in the discrimination of patients with severe depression was assessed based on the AUC values, which is also presented graphically by the ROC curve." (PMID 39595067, 2024). "Elevated levels of inflammatory markers, especially interleukins (IL-6, IL-1α) and tumor necrosis factor-alpha (TNF α), have been identified in patients with major depressive disorder compared to the findings in healthy controls." (PMID 39595067, 2024). "A number of the selected hub genes in our study have been previously reported to be related to FMS or depression, including GRIK1&2, NGF, KCNQ2, GRIA1, TRPV4, IL1A, and GABAA receptors." (PMID 37065490, 2023). "The inflammatory etiology of fatigue and depression in MS was supported by evidence of increased serum and CSF concentration of inflammatory mediators such as TNF, interleukins (IL-1a, IL-1b, IL-6), IFNγ, and neopterin." (PMID 35242093, 2021). "In contrast, we observed significantly decreased levels of pro-inflammatory cytokines IL-1α, TNF-α and chemokine MIP-3α in Abuse+Depression groups compared to Controls." (PMID 29894487, 2018). "In this study, we found that the CMS protocol increased Iba1 expression as well as TNF-α, IL-1α, and IL-1β levels in the hippocampus or serum, while MOs successfully inhibited this effect in CMS-exposed mice, leading to the attenuation of depression-like symptoms." (PMID 36052143, 2022). "There was a not significant effect of BMI (F(3.53) = 0.671; p > 0.05) and depression (F(1.53) = 1.456; p > 0.05) on IL-1α, as well as a not significant interaction effect either." (PMID 31450770, 2019). "IL1a is a potent inflammatory cytokine and a key mediator of brain inflammation whereas IL6 is a pro-inflammatory cytokine involved in depression." (PMID 28659758, 2017). "The main question is whether plasma concentrations of pro-inflammatory cytokines (IL-6, IL-1α, and TNF-α) can serve as predictive biomarkers for depression severity and whether these concentrations are modulated by gender among patients diagnosed with major depressive disorder (MDD)." (PMID 39595067, 2024). "Similar to the findings in CP/CPPS patients, elevated levels of IL-1α, IL-1β, IL-4, IL-13, and TNF-α were observed in CP/CPPS rat prostates, and these elevated cytokine levels showed a positive trend in their correlation with anxiety, depression, and memory impairment." (PMID 27334333, 2016). "Materials and Methods: Inflammatory markers (IL-6, IL-1α, and TNF-α) were measured in a sample of 92 patients hospitalized at the Socola Institute of Psychiatry in Iasi, Romania, and compared to a control group with no depression or inflammatory conditions (n = 76)." (PMID 39595067, 2024).